GPX4 (glutathione peroxidase 4)
Diseases named in the same sentence as GPX4 in open-access papers (continued):
Sharing a sentence is not in itself a finding about the gene and the disease.
tumor (continued). "Given the low expression of GPX4 in some tumors, the induction of tumor cell death by affecting FSP1 has attracted attention, and the development of specific agonists or inhibitors of FSP1 will provide alternative opportunities for tumor therapy." (PMID 36275899, 2022). "The downstream effectors xCT and GPX4 are upregulated and effectively reduce the accumulation of lipid ROS in tumor cells, protecting them from ferroptosis." (PMID 35105963, 2022). "By immunohistochemistry, a significant increase of ASCL4 and ALDH1A3 expression and a significant decrease of GPX4 expression was observed when comparing primary and corresponding recurrent tumor." (PMID 35530303, 2022). "In groups ZD2767P+CPG2 and ZD2767P+CPG2+US, the apoptosis level (TUNEL) in tumor tissues was increased, but the GPX4 level was decreased (A549: p < 0.0001 for each; A549/DDP: p < 0.0001 for each)." (PMID 36388164, 2022). "Researches have reported that downregulated GPX4 promotes tumor sensitive to ferroptosis, while upregulated GPX4 decreases ferroptosis sensitivity." (PMID 35775079, 2022). "GPX4 is closely related to the tumor stage and promotes acquired chemoresistance by suppressing ferroptosis." (PMID 35236309, 2022). "Combination with Gpx4 deletion or the administration of high-iron diet accelerated pancreatic tumorigenesis, as characterized by an elevated stromal response, increased tumor invasion and metastasis, and decreased survival." (PMID 35065965, 2022). "Protein expression of GPX4 ≥ 5% of tumor cell detected by IHC staining was defined “positive” and observed in 192 (72.5%) specimens." (PMID 36443446, 2022). "Specifically, D-2- hydroxyglutaric acid, a metabolite produced by mutant IDH1 in tumor cells, reduces the expression of antioxidant GPX4 in tumor cells, thus enhancing the ferroptosis sensitivity induced by Erastin." (PMID 36237575, 2022). "The pharmacological targeting of FSP1 has a strong synergistic effect with GPX4 inhibitors, which can trigger the ferroptosis of multiple tumor entities." (PMID 35688814, 2022). "Multiparametric IHC analysis also confirmed that GPX4 was highly expressed in omental metastatic tumor cells." (PMID 35547771, 2022). "A number of studies have shown that inhibiting the expression of the GPX4 gene can effectively kill tumor cells through ferroptosis." (PMID 34975326, 2022). "Mao also demonstrated that Brequinar, an inhibitor of DHODH, impeded the proliferation of tumor cells with low GPX4 expression." (PMID 35155264, 2022). "Then, we extracted the proteins from subcutaneously transplanted tumours and conducted western blotting experiments, which also confirmed reduced FOXM1, STAT3, p-STAT3 and GPX4 expression in subcutaneous tumours from the TST treatment group." (PMID 35859150, 2022). "The administration of LDL–DHA at a dose of 2.5 mg/kg for three consecutive days inhibited the tumor growth by increasing lipid hydroperoxides and downregulating GPx-4." (PMID 36296934, 2022). "We observed that combination treatment with doxorubicin plus FO/Se resulted in higher tumor expression of Sel-H, Sel-W, and GPx4 than did doxorubicin alone." (PMID 36483592, 2022). "While RSL3 promotes ferroptosis via inhibition of GPX4, it also appears to enhance tumor cell DNA damage." (PMID 36371529, 2022). "High levels of Glutathione peroxidase 4 (GPX4), which inhibits ferroptosis, a lipid peroxidation-mediated cell death in tumor cells, are associated with poor prognosis in cancer patients." (PMID 35954274, 2022). "There is a growing body of literature that recognizes activation of ferroptosis can inhibit tumor cell proliferation, and GPX4, a phospholipid hydroperoxide glutathione peroxidase, can inhibit ferroptosis in tumor cells." (PMID 36133791, 2022). "Conversely, the GPX4 inhibitors RSL3 and ML210/162 can cause ferroptosis in resistant tumor cell lines and are lethal to residual tumor cells." (PMID 35990689, 2022).
tumor (continued). "Dichloroacetate (DCA) combined with albiziabioside A (AlbA) can inhibit GPX4 and induce ferroptosis to inhibit tumor progression." (PMID 36467032, 2022). "Overexpression of GPX4 endows tumour cells with resistance to ROS-induced cell death, while silencing GPX4 sensitizes tumour cells." (PMID 35574340, 2022). "The ferroptosis activator RSL3 can induce ferroptosis in tumor cells by silencing or inhibiting GPX4 expression." (PMID 36185243, 2022). "The cutoff value for defining GPX4 positivity was determined according to the percentage of tumor stained in the microscopic field." (PMID 36443446, 2022). "These in vitro and in vivo results indicated the important role of GPX4 in promoting tumor progression by enhancing the capacities of proliferation and colony formation." (PMID 35105963, 2022). "On the contrary, inhibiting GPX4 would enhance lipid peroxidation and trigger ferroptosis-induced cell death in the development and progression of tumor." (PMID 36213827, 2022). "Collectively, our in vivo results further verified that ANGPTL4 was essential for hypoxic exosomes induced radioresistance in tumours at least partly through GPX4-mediated ferroptosis inhibition." (PMID 36050447, 2022). "Targeting ferroptosis-related genes such as GPX4, AIFM2, and HDAC can modulate oxidative stress and thus confer susceptibility to ferroptosis in tumor cells." (PMID 35360452, 2021). "Recent studies indicate that ferroptosis, like apoptosis acts as a new tool for suppressing tumor growth; inhibitors of GPX4 have been proposed as promising drugs in cancer therapy." (PMID 34131139, 2021). "RSL3@COF-Fc NPs efficiently reduce tumor growth as well as GPX4 activity and GSH content, while increasing the MDA amounts." (PMID 34834199, 2021). "Conversely, protein levels of NRF2 and GPX4 of xenograft tumor tissues were significantly reduced by ZVI-NP exposure." (PMID 34093872, 2021). "Previous studies showed that an increase in GPX4 also inhibits cell death and promotes the tolerance of tumor cells to lipid peroxidation, contrasting our results." (PMID 34178024, 2021). "Consistent with our in vitro observations, SFRS9 promoted the growth of tumors and SFRS9 knockdown significantly induced tumor growth inhibition in nude mice, and GPX4 expression in tumor tissues was consistent with that of SFRS9." (PMID 34336668, 2021). "Most studies of these drugs have looked at the activity of GPX4/ferroptosis inhibitors in vitro, or in some cases on primary tumor growth." (PMID 34429409, 2021). "A study reported that inhibition of GPX4 led to ferroptosis especially in drug-resistant tumor cells." (PMID 34621297, 2021). "Erastin-induced ferroptosis through GPX4 inactivation played an important role in inhibiting tumor growth and killing tumor cells." (PMID 34053456, 2021). "We show that pharmacologic inhibition of mTORC1 decreases GPX4 protein levels, sensitizes cancer cells to ferroptosis, and synergizes with ferroptosis inducers to suppress patient-derived xenograft tumor growth in vivo." (PMID 33707434, 2021). "Mechanistically, blocking enzymes such as DECR1, PANX2 and GPX4 can inhibit tumor growth with universal implications in understanding both resistance and metabolic events." (PMID 33596934, 2021). "We observed that high expression levels of GPX4 and AIFM2 were significantly associated with tumor purity in ESCA (R = 0.25, p = 6.93e-04; R = 0.279, p = 1.43e-04) and in HNSC, respectively (R = 0.223, p = 5.37e-07; R = 0.205, p = 4.41e-06)." (PMID 34722530, 2021). "The cyst(e)ine/glutathione (GSH)/glutathione peroxidase 4 (GPX4) axis is the most frequently targeted pathway to trigger the ferroptosis cascade and suppress tumor growth." (PMID 34373463, 2021). "TFAP2C upregulates the GPX4 gene in tumor cells and regulates some ferroptosis regulators, such as epidermal growth factor receptor (EGFR), CDKN1A, and YAP1, thereby negatively regulating ferroptosis." (PMID 34804126, 2021).
tumor (continued). "It has been found that GPX4 is closely related to tumor size and classifying in LUAD, and the higher the malignancy the lower the degree of lipid peroxidation of the tumor is." (PMID 34805165, 2021). "On the contrary, the up-regulation or activation of intracellular GPX4 level can induce cell resistance to ferroptosis, suppress the therapeutic effects of drugs, and finally result in tumor resistance to chemotherapeutics." (PMID 33819186, 2021). "It has been suggested that (i) mTORC1 inhibition synergizes with ferroptosis inducers to suppress tumor growth, (ii) mTORC1 inhibition decreases GPX4 levels and (iii) RSL3 blocks mTOR activation." (PMID 34716292, 2021). "They found that simvastatin, as expected, inhibited GPX4 mRNA and protein expression and reduced tumor volume." (PMID 34671620, 2021). "The results showed that GPX4 expression was upregulated in tumor tissues (p < 0.01), and GPX4 expression was upregulated in 26 CRC tissues compared with adjacent normal tissues (p < 0.01)." (PMID 34601499, 2021). "To further confirm the essential role of Gpx4 in PTENα-mediated tumor immune escape, we used shRNA to knock down the endogenous Gpx4 expression in Pten−/− B16 cells, which was subsequently stable transfected with PTENα." (PMID 34446716, 2021). "Research indicates that, the GPX4 levels in tumor tissues of advanced CRC patients are remarkably higher than those in para-carcinoma tissues." (PMID 33819186, 2021). "As the most significant CALU-associated gene, HSPA5 has been demonstrated to play a vital role in tumor cell’s ferroptosis resistance through interaction with GPX4, a critical gene for ferroptosis." (PMID 34150647, 2021). "This ability of selective accumulation of toxic lipid peroxides to induce apoptosis/ferroptosis of tumor cells seems to be dependent on the glutathione peroxidase (GPX4) levels in the cells." (PMID 33567774, 2021). "Inhibiting GPX4 by resibufogenin (RB) induced ferroptotic cancer cell death and suppressed tumor growth in vivo." (PMID 34722530, 2021). "The protein level of GPX4 in tumor was decreased significantly in compound 13-treated group compared with vehicle group." (PMID 33472669, 2021). "For example, GPX4 is believed to be the main enzyme preventing ferroptosis, and the induction of ferroptosis by suppressing GPX4 has been a therapeutic method for tumor cell death." (PMID 34362387, 2021). "At present, the researches on ferroptosis-antagonizing tumor resistance mainly focus on the inhibition of ferroptosis defense system, such as GPX4." (PMID 34485112, 2021). "Inhibition of a lipid peroxidase pathway GPX4 induces ferroptosis in therapy-resistant cancer cells and prevents tumor relapse in vivo." (PMID 34749765, 2021). "The tumor growth inhibition and the reduced GPX4 activity are counteracted by the co-administration of iron chelators (i.e., FERR inhibitor)." (PMID 34834199, 2021). "Our preclinical studies using PDXs also showed that combined treatment with mTORC1 inhibitor and FIN synergistically depleted GPX4 and induced ferroptosis in vivo, resulting in more potent tumor growth suppression than either treatment alone." (PMID 33707434, 2021). "cAMP response element-binding protein (CREB) is also an upregulated oncogene in LUAD tissues that positively regulates the expression of GPX4, and their levels are closely related to tumor size and stage." (PMID 34926310, 2021). "The mRNA expression of KEAP1, HSBP1, SAT1, CISD1, and GPX4 were significantly different between tumor and the adjacent tissues." (PMID 34692692, 2021).
tumor (continued). "By analyzing the gene expression data of immune markers in the TIMER database, we investigated the association between the levels of SLC7A11, GPX4, and AIFM2 and the status of tumor-infiltrating immune cells in ESCA, HNSC, COAD, READ, STAD, and LUAD." (PMID 34722530, 2021). "In this regard, withaferin A and altretamine (FDA-approved drugs for cancer therapy), with function to inhibit GPX4, exhibited favorable anti-tumor activity in animal models, representing another option for targeting GPX4 in vivo." (PMID 33891303, 2021). "Recently, it has been demonstrated that Gpx4 KO significantly impairs tumour growth upon Fer-1 withdrawal, whilst additional Fsp1 KO enhances this effect." (PMID 31936571, 2020). "A novel conjugate AlbA-DCA was developed via inhibition of the GPX4 pathway and elimination of procarcinogenic M2-TAMs to suppress tumor progression in breast cancer." (PMID 33102227, 2020). "GPX4 is highly expressed in tumor tissues, compared with adjacent tissues, and was inverse correlated with the patient's prognosis." (PMID 33425217, 2020). "Because median serum TGF-β1 levels in HCC patients are approximately 13.7 ng/mL35, it is relevant that TGF-β1 secreted from tumor microenvironment can induce xCT repression and enhance GPX4 inhibitor-mediated cell death in these HCC cells." (PMID 32471991, 2020). "In summary, our results demonstrated that PdPT is a broad-spectrum inhibitor of DUBs that suppresses tumor growth through activation of caspase-dependent apoptosis and GPX4 degradation-dependent ferroptosis." (PMID 32596160, 2020). "Given that macrophages are major players in the early stages of pancreatic tumorigenesis, we next tested the impact of Gpx4 depletion or a high-iron diet on macrophage infiltration and activation in the tumor microenvironment." (PMID 33311482, 2020). "After constructing the subcutaneous tumor model in nude mice, sh-GPX4 treatment significantly reduced the growth rate of tumor in nude mice, and further increased the inhibitory effect of gefitinib on tumor." (PMID 33425751, 2020). "Rescue of ferroptosis through GPX4 overexpression or ACSL4 silencing in tumor cells was reported to alleviate neutrophil-induced tumor cell killing and necrosis, inhibited tumor aggressiveness and improved mouse survival." (PMID 33679721, 2020). "Second, ferroptosis-driven nanotherapeutics are used as carriers of chemotherapeutic drugs or ferroptosis inducers to inhibit the expression of the GSH/GPX4 system in tumor cells." (PMID 33102227, 2020). "As reported, inhibition of tumor propellant GPX4 enhances anticancer effect of chemotherapeutic drugs." (PMID 33425751, 2020). "In this mouse study, the authors show that diets high in iron or depletion of the antioxidant Gpx4 potentiates pancreatic damage and tumour formation by activating the DNA damage pathway and recruiting macrophages to the pancreas." (PMID 33311482, 2020). "We found that the amount of GPX4 is less in tumor cells close to the necrotic area than in the cellular tumor region in LN229TAZ(4SA) tumors." (PMID 33110073, 2020). "The suppression of GPX4 by sorafenib combined with the tumor site-specific Fenton reaction induced by Fe ions results in a powerful tumor-specific ferroptosis." (PMID 33102227, 2020). "Treatment with erastin induced ferroptosis and decreased the concentration of glutathione and GPX4 protein expression levels in the two tumor cell lines." (PMID 31800616, 2019). "Contrary to the GPX4 protein expression, the intracellular and tumor glutathione concentrations in both the adenocarcinoma cell lines markedly decreased after the treatment with erastin." (PMID 31800616, 2019). "On the other hand, many cancer cells rely on GPX4 to evade ferroptosis, rendering it an attractive target for tumor therapy." (PMID 30534534, 2018). "In vivo, transplanted GPx4-overexpressing HCC cells formed smaller tumors which displayed reduced tumor cell proliferation and reduced macrophage density." (PMID 29515790, 2018).
tumor (continued). "Complementary, overexpression of GPx4 in HCC tumor cells lowered IL-8 levels at base line and upon LOOH treatment." (PMID 29515790, 2018). "To analyze the pathways differentially regulated by GPx4 in human HCCs, we stratified patients according to their GPx4 expression levels in tumor, defined quartiles with the high and the low GPx4 expression and applied Ingenuity Pathway Analysis." (PMID 29515790, 2018). "We have further compared relative GPx4 expression between tumor tissue and surrounding tissue in HCC patients with different molecular subclasses." (PMID 29515790, 2018). "GPx4-overexpressing cells displayed impaired tumor growth, reduced proliferation, altered angiogenesis and decreased expression of clinically relevant cytokine interleukin-8 and C-reactive protein." (PMID 29515790, 2018). "For example, accumulation of GPx4 in tumor tissue as compared to surrounding tissue has been described in hepatitis C-related liver tumors." (PMID 29515790, 2018). "In the context of cancer, however, GPx4 also appears to be a tumor suppressor in the majority of cases." (PMID 27023612, 2016). "Overexpression of Gpx4 leads to reduced tumor growth of weakly tumorigenic L929 fibrosarcoma cells and pancreatic cancer cells, possibly mediated by inhibition of NF-κB activation." (PMID 27023612, 2016). "The reduction of GPX4 is pro-oncogenic since GPX4 has been shown to halt tumour proliferation and progression." (PMID 24728830, 2014). "Therapeutically, targeting phosphatidylcholine synthesis and remodeling combined with ferroptosis inducers or glutathione peroxidase 4 inhibitors could sensitize tumors to oxidative cell death while reprogramming stromal elements toward anti-tumor activity." (PMID 41684458, 2026). "This underscores the role of CD8+ T cells in promoting tumor cell ferroptosis and suggests that targeting the XCT/GSH/GPX4 pathway in combination with anti‐PD‐1/PD‐L1 antibodies may represent an effective tumor immunotherapy strategy." (PMID 41560416, 2026). "Quadricep RNA seq analysis revealed that expression of inflammatory genes was elevated in wildtype tumour-bearing mice when compared to control mice, and the expression of these genes was reduced in tumour-bearing GPx4 Tg mice compared to wildtype tumour-bearing mice." (PMID 41854231, 2026). "We next examined whether GPX4–/– CD8+ T cells were responsive to α4-1BB treatment in tumor-bearing mice in an adoptive transfer system." (PMID 40178905, 2025). "Recent studies suggest that altretamine inhibits GPX4, leading to ROS and lipid peroxide accumulation and triggering ferroptosis in tumor cells, although the precise mechanism remains unclear." (PMID 40424719, 2025). "This approach adeptly circumvents erastin resistance through the targeted downregulation of the antioxidase GPX4 and the upregulation of the tumor suppressor hypermethylated in cancer 1, precisely exploiting the metabolic susceptibilities of these cancerous cells." (PMID 40427552, 2025). "Furthermore, Tregs with GPX4 deletion promote the cell death of intratumoural Tregs while improving immune responses against tumours." (PMID 40045458, 2025). "Preclinical evidence showed that some marine polysaccharides can indirectly inhibit GPX4 expression and promote lipid peroxidation in tumor cells by enhancing CD8+ T cell-mediated IFN-γ secretion, which provides theoretical support for immune-ferroptosis combined therapy." (PMID 40559667, 2025). "Ferroptosis or cuproptosis inducers severely weaken the antioxidant defenses of tumor cells by inhibiting GPX4 or depleting GSH, allowing the ROS generated by radiotherapy to cause more lasting and extensive damage, thereby significantly enhancing the killing effect of RT." (PMID 41201667, 2025).